INS (insulin)
Diseases named in the same sentence as INS in open-access papers (continued):
Sharing a sentence is not in itself a finding about the gene and the disease.
type 2 diabetes (continued). "Type 2 diabetes mellitus (T2DM) is a type of systemic metabolic disorder characterized by absolute or relative reduction in insulin secretion (or insulin resistance) caused by defects in islet β‐cell function, which may occur as a result of genetic, environmental, and immune factors." (PMID 31265177, 2019). "Although it has been reported that insulin sensitivity and insulin secretion decrease with the progression of type 2 diabetes, the application of this model will lead to a more precise mechanism of how changes of parameters in the model can explain the progression of insulin intolerance." (PMID 31508240, 2019). "Moreover, T3 administration decreased blood glucose level within 2 h and increased insulin sensitivity, insulin synthesis and storage in pancreatic beta cells, as well as increased plasma insulin level in obese mouse model of type 2 diabetes." (PMID 30945110, 2019). "In some AD patients, insulin signaling is reduced overall accompanied by type 2 diabetes." (PMID 30652125, 2019). "The classes currently available are insulin and insulin analogues for type-1/type-2 diabetes, sulfonylureas, glinides, biguinides, glitazones (thiazolidine diones), and α–glycosidase inhibitors for type-2 diabetes (T2D)." (PMID 31324043, 2019). "Type 2 diabetes (T2D) is a highly prevalent metabolic disorder, characterized by complex disturbances in glucose and lipid metabolism resulting from a combination of resistance to insulin action and an inadequate insulin secretion response." (PMID 31065046, 2019). "Moreover, ABCG1 hosts many kinds of cardio-metabolic phenotypes, including glucose and insulin measurements, type 2 diabetes, and obesity, which are strongly related to cardiovascular diseases." (PMID 31823830, 2019). "The Belury group were the first to show that co-treatment with mixed CLA and the thiazolidinedione rosiglitazone, a PPARγ agonist that promotes insulin sensitivity and is used clinically to treat type 2 diabetes, improves insulin sensitivity in mice that are undergoing weight gain." (PMID 30754681, 2019). "Data from a small number of studies indicate that LADA patients have worse glycemic control than patients with type 2 diabetes which may be due to the limited endogenous insulin production." (PMID 30971952, 2019). "Likewise, in type 2 diabetes patients, the relative safety of insulin therapy has been under discussion." (PMID 30742240, 2019). "Zinc is essential for the formation of both the stored and active forms of insulin and may be involved in the development or progression of both type 1 and type 2 diabetes." (PMID 31983911, 2019). "Obesity results from ingestion of excess energy which does not get expended and is a strong risk factor for type 2 diabetes, the latter of which is characterised by high blood sugar levels, insulin resistance and relative lack of insulin." (PMID 31022973, 2019). "MTZ is a hepatic insulin sensitizer that lowers blood glucose to treat type 2 diabetes." (PMID 31354482, 2019). "These SNPs have not been previously reported to be associated with type 2 diabetes risk or insulin sensitivity." (PMID 30641161, 2019). "Furthermore, GSK-3 expression is increased in the skeletal muscle of type 2 diabetic patients and negatively correlated to whole-body insulin action." (PMID 30469501, 2018). "Several miRNAs have recently been implicated in glucose metabolism, but the roles of miRNAs in insulin-resistant conditions, such as obesity or type 2 diabetes, are largely unknown." (PMID 29364977, 2018). "Reducing excess glucose combined with improving insulin sensitivity could be an ideal combination for obese patients with type 2 diabetes (T2D)." (PMID 30072956, 2018). "In adult-onset diabetes, the detection of GADA together with insulinoma-associated antigen-2 autoantibodies (IA-2A) or zinc transporter-8 autoantibodies (ZnT8A) is highly predictive of the need for insulin therapy." (PMID 29619531, 2018).
type 2 diabetes (continued). "Patience is a virtue when treating patients with type 2 diabetes who are on insulin." (PMID 31404422, 2018). "We therefore tested the hypothesis that overweight individuals with type 2 diabetes on a 12 week Paleolithic diet would exhibit a decrease in liver fat and IMCL content, associated with an improvement in hepatic and peripheral insulin sensitivity." (PMID 29696296, 2018). "Furthermore, approximately 25% of adults with type 1 or insulin-treated type 2 diabetes experience injection-related anxiety." (PMID 29347915, 2018). "R. is a 69-year-old woman with type 2 diabetes who has been treated with insulin since 2011." (PMID 29682315, 2018). "Prevalent type 2 diabetes cases were defined as having at least one E11 or T90 diagnosis of type 2 diabetes and one or more prescriptions of non-insulin glucose-lowering drugs, or being registered with a type 2 diabetes diagnosis on at least at two different occasions." (PMID 29995214, 2018). "Moreover, when this phloratannin was administered intraperitoneally in the db/db mouse model of type 2 diabetes, significantly lower blood glucose and insulin concentrations were found compared to the untreated control group." (PMID 30060542, 2018). "A previous study has found out that miR-144-3p was highly up-regulated in type 2 diabetes (T2D) and could impair insulin signaling." (PMID 30619490, 2018). "Hermansen K, Davies M, Derezinski T, Martinez Ravn G, Clauson P, Home P. A 26-week, randomized, parallel, treat-to-target trial comparing insulin detemir with NPH insulin as add-on therapy to oral glucose-lowering drugs in insulin-naive people with type 2 diabetes." (PMID 29527102, 2018). "People with uncontrolled type 2 diabetes receiving a DPPIVi and basal insulin may benefit from Gla-300 therapy." (PMID 29370218, 2018). "Both type II diabetes and insulin resistant mice show disruption of GLUT4 expression." (PMID 29522441, 2018). "However, peptides such as tigerinin-1R and alyteserin-2a, which are partially deficient in antimicrobial activity, are able to promote the secretion of insulin, showing a potential for use in the treatment to type 2 diabetes." (PMID 29360748, 2018). "The metabolic and cellular changes may restore abnormalities in circulating glucose levels and insulin sensitivity in individuals with type 2 diabetes that receive the first generation TZDs or MSDC-0160." (PMID 29793507, 2018). "In the Sweden study, 25% patients with type 2 diabetes had insulin prescribed within 6 years of starting oral hypoglycemic agents and this figure rose to 42% within 10 years, corresponding to an annual rate of insulin initiation of 4%." (PMID 30327785, 2018). "Recent studies have further shown that genetic risk variants for type 2 diabetes are more strongly associated with defect insulin secretion rather than insulin action." (PMID 29274011, 2018). "In a population-based cohort with insulin-treated type 2 diabetes, self-reported hypoglycaemia was twice as frequent in those with rCP < 200 pmol/l (OR 2.0, p < 0.001) and the rate of episodes resulting in loss of consciousness or seizure was five times higher (OR 5.0, p = 0.001)." (PMID 28983693, 2018). "Therefore, stimulating the insulin release benefits the treatment of type 2 diabetes and obesity significantly." (PMID 29516672, 2018). "Insulin injections are the mainstream treatment for patients with type 2 diabetes in China." (PMID 29699587, 2018). "Altered activation of PI3K and SREBP-1c may explain the defective regulation of miR-1 and miR-133a expression in response to insulin in muscle of type-2 diabetic patients." (PMID 29995913, 2018). "A nonpositive insulin response at 30 min on the OGTT may reflect an impairment of early insulin response, which is one of the primary pathophysiologic changes of type 2 diabetes." (PMID 29765987, 2018).
type 2 diabetes (continued). "Negative energy balance in type 2 diabetes causes a profound fall in liver fat content resulting in normalisation of hepatic insulin sensitivity within 7 days." (PMID 29143063, 2018). "Identifying dietary factors that determine insulin sensitivity and secretion in children entering puberty may provide valuable information for the early prevention of type 2 diabetes." (PMID 30383280, 2018). "Actually, activation of these targets by RSV as a drug led to cellular and enzymatic phenomena including decreased lipid accumulation, inflammation, and oxidative damage in liver, muscle, and adipocyte tissues and finally led to insulin action improvement in type 2 diabetes." (PMID 30510749, 2018). "However, injectable medications other than insulin are now used to treat type 2 diabetes, primarily medications in the class of glucagon-like peptide-1 (GLP-1) receptor agonists." (PMID 30294714, 2018). "Our results demonstrate that patients with insulin-treated type 2 diabetes but low C-peptide levels have markedly increased incidence of hypoglycaemia in comparison to those with retained C-peptide, whether measured by CGM or self-reported." (PMID 28983693, 2018). "Severe insulin deficiency can occur in insulin-treated patients who have clinical features consistent with type 2 diabetes, but the deficiency is usually not recognised." (PMID 28983693, 2018). "Rosenstock J, Davies M, Home PD, Larsen J, Koenen C, Schernthaner G. A randomised, 52-week, treat-to-target trial comparing insulin detemir with insulin glargine when administered as add-on to glucose-lowering drugs in insulin-naïve people with type 2 diabetes." (PMID 29527102, 2018). "Strategies aimed at increasing access to and intake of vegetables and fruits may lead to improved insulin sensitivity over time and contribute to the prevention of type 2 diabetes." (PMID 30383280, 2018). "However, lean endurance-trained athletes exhibit IMCL content measured at rest that is nearly as high as that of people with type 2 diabetes, but with concomitant normal insulin sensitivity, referred to as the athlete’s paradox." (PMID 29696296, 2018). "Reduced insulin sensitivity is a precursor for the development of Type 2 diabetes in the cat." (PMID 29971046, 2018). "In addition to inflammation having a prominent role in diabetic retinal pathology, impaired insulin signaling occurs in the diabetic retina, particularly in type 2 diabetes." (PMID 30116147, 2018). "The results can therefore not be transferred to overweight, obese, and elderly people or patients with type 2 diabetes, because impaired glucose metabolism might lead to a more pronounced impairment of postprandial insulin sensitivity with BM-intervention." (PMID 29695707, 2018). "Thus, obesity and the inflammation axis are part of a vicious cycle that develops insulin resistance (IR) in various insulin-sensitive tissues, such as the liver, skeletal muscles, and adipose tissues, leading to type 2 diabetes (T2D)." (PMID 29659527, 2018). "Additionally, the insulin related pathway findings are consistent with the major role of insulin signaling in modulating the pathogenesis of both type 2 diabetes and AS." (PMID 30390707, 2018). "Moreover, epidemiological studies have demonstrated that both type 1 diabetes (insulin-deficient, T1DM) and type 2 diabetes (insulin-resistant, T2DM) are co-morbid with cognitive impairment, including dementia and Alzheimer’s disease (AD)." (PMID 30333718, 2018). "Type 2 diabetes results from insulin resistance and the body's inability to respond to insulin." (PMID 30534081, 2018). "Type 2 diabetes usually results from reduced insulin secretion or decreased sensitivity to insulin." (PMID 30386536, 2018).
type 2 diabetes (continued). "Klotho-regulated serine (RELA) phosphorylation can negatively regulate the production of NF-κB-linked inflammatory proteins and upregulate the cAMP/PKA pathway, which suppressing inflammation and improving insulin sensitivity, significantly regulating type I and type II diabetes." (PMID 30521536, 2018). "While type 1 diabetes has a very complexdaily glucose pattern, the approach to type 2 diabetics on insulin could become simplified." (PMID 31404422, 2018). "We also found that ER is more often phosphorylated in women using insulin with type 2 diabetes compared to type 1 diabetes, which is in line with our previous findings that type 2 diabetes insulin users had more often ER-positive tumors compared to women with type 1 diabetes." (PMID 29486734, 2018). "Notably Type II diabetes mellitus and Insulin signaling pathways were respectively over-activated and under-activated." (PMID 30022049, 2018). "This hypoglycemic effect of exercise may be due to the increase of insulin sensitivity and improvement of beta-cell function in type 2 diabetic rats." (PMID 29920546, 2018). "Systems biology approaches identified HNF1A, PDX1 and REST as drivers of gene co-expression modules correlated with impaired insulin secretion or glucose tolerance, and 14 out of 19 differentially expressed type 2 diabetic islet signature genes were enriched in these modules." (PMID 29185012, 2018). "The results of other studies that in part were similar to our own, also demonstrated a decreased ATSLC2A4 expression in animal models of type 2 diabetes and in insulin-resistant humans, which may serve to support our findings." (PMID 29417372, 2018). "Consensus statement on choice of insulin therapy in type 2 diabetes." (PMID 29527102, 2018). "NICE (2015) recommends that women with pre-existing type 2 diabetes can receive metformin as an adjunct or alternative to insulin in the preconception period and during pregnancy when the likely benefits from improved glucose control outweigh the potential for harm." (PMID 29973490, 2018). "However, a range of injectable medications other than insulin are now used to treat type 2 diabetes." (PMID 30294714, 2018). "Owens DR, Traylor L, Mullins P, Landgraf W. Patient-level meta-analysis of efficacy and hypoglycaemia in people with type 2 diabetes initiating insulin glargine 100 U/mL or neutral protamine Hagedorn insulin analysed according to concomitant oral antidiabetes therapy." (PMID 29527102, 2018). "In addition, compared with lean individuals, it is known that [18F] FDG uptake in BAT is lower in obese individuals, in individuals with type 2 diabetes and in increasing age, likely due to increased insulin resistance." (PMID 30145664, 2018). "Insulin therapy is a cornerstone therapy for many patients with type 2 diabetes." (PMID 30564289, 2018). "However, in postmenopausal women, estrogen-based replacement therapies improve insulin sensitivity and strongly reduce the incidence of type 2 diabetes." (PMID 29692809, 2018). "The patient with type-2 diabetes has a low level of insulin due to post-prandial hyperglycemia." (PMID 30524692, 2018). "Understanding the mechanism of action and function of adipokines in mediating insulin sensitivity in skeletal muscle may lead to the development of novel therapeutics for patients with type 2 diabetes." (PMID 29760587, 2018). "Therefore, reduced first-phase insulin secretion is present in the early stage of impaired glucose metabolism and has been well characterized as a primary defect in the development of type 2 diabetes." (PMID 30581872, 2018). "PPAR-γ might improve insulin sensitivity and lipid profiles in patients with type 2 diabetes as well as in diabetic rodent models." (PMID 30546347, 2018). "Impaired insulin-stimulated glucose disposal is a common metabolic derangement in aged and obese skeletal muscle, with this insulin resistance being central to the pathophysiology of type 2 diabetes (T2D)." (PMID 29997524, 2018).
type 2 diabetes (continued). "Type 1 diabetes and severe type 2 diabetes depend on insulin injection." (PMID 30423891, 2018). "Thus, despite higher insulin levels, patients with type 2 diabetes show little reactivity to insulin, making them functionally equivalent to patients with type 1 diabetes." (PMID 30618559, 2018). "Lastly, we found an association between altered insulin signalling and ER-mitochondria interactions in human myotubes from obese subjects with or without type 2 diabetes, compared to healthy lean subjects." (PMID 29523782, 2018). "In humans, SGLT-2 inhibitors are used in the treatment of type 2 diabetes, and have been shown consistently to reduce blood glucose concentrations and improve insulin sensitivity without causing hypoglycemia." (PMID 30212530, 2018). "Within 10 years after diagnosis, about 50% of type 2 diabetes patients start with insulin therapy." (PMID 30081574, 2018). "Furthermore drugs used to treat type II diabetes, either via improving insulin sensitivity or increasing the release of insulin, impact positively on learning and memory." (PMID 30097632, 2018). "Severe insulin deficiency was not uncommon in participants with insulin-treated type 2 diabetes in our cohort, occurring in 13% of participants even when strict clinical criteria for classification were applied." (PMID 28983693, 2018). "In addition, insulin-treated patients in the current study comprise a heterogeneous group – i.e. some with long-standing Type 1 diabetes, and others with Type 2 diabetes and more recent initiation of insulin treatment." (PMID 28918198, 2018). "Insulin pathophysiology has been associated with inflammatory markers independent of BMI in subjects at risk of type 2 diabetes." (PMID 29566726, 2018). "In type 2 diabetes, sinapic acid increased the sensitivity of cells to insulin." (PMID 29967666, 2018). "Finally, this analysis did not evaluate the effects of teneligliptin in combination with another therapeutic agent for type 2 diabetes such as insulin, thiazolidinedione, and sodium glucose co-transporter 2 inhibitors." (PMID 29435909, 2018). "A prospective cohort study observed that females reporting adult-onset diabetes were at an increased risk of NHL if they used insulin, but to the best of our knowledge no studies have assessed endogenous insulin levels and NHL." (PMID 29713614, 2018). "In Drosophila type 2 diabetes models can be generated by two different strategies: by downregulating conserved genes working on insulin pathways as for example the insulin receptor InR, the insulin substrate receptor chico/IRS1, Akt1, PI3K, and by feeding flies with a high sugar rich diet." (PMID 30271425, 2018). "Patients were treated for type 2 diabetes with a wide range of non-insulin injectable medications." (PMID 30294714, 2018). "Previous reports on studies in rodents and humans have shown that an increased systemic supply of protein or amino acids negatively affects systemic insulin action, and epidemiological studies demonstrate that dietary protein intake and type 2 diabetes incidence are positively correlated in humans." (PMID 29507597, 2018). "During conditions of energy surplus and physical inactivity, skeletal muscle becomes insulin resistant; this condition may progress into type 2 diabetes and cardiovascular diseases." (PMID 30183740, 2018). "A hypothesized mechanism linking increased levels of BCAAs and type 2 diabetes involved leucine-mediated activation of the mammalian target of rapamycin complex 1 (mTORC1), which resulted in the uncoupling of insulin signalling at an early stage." (PMID 30005063, 2018). "Thus, type 2 diabetes and critical care hyperglycemia can both feature reduced insulin sensitivity, reduced insulin clearance, and insufficiently increased insulin secretion, with resulting hyperglycemia." (PMID 30071851, 2018). "Animal studies and experimental studies have shown that adiponectin improves insulin sensitivity, thus may prevent the development of type 2 diabetes (T2D)." (PMID 29321603, 2018).